MIR541 (microRNA 541)
Synonyms: hsa-mir-541; MIRN541; mir-541
Gene: MicroRNA gene on chromosome 14 (101,064,495 to 101,064,578, forward strand). Ensembl gene ENSG00000216179.
Gene Ontology:
Biological process: long-term synaptic potentiation; miRNA-mediated post-transcriptional gene silencing; negative regulation of gene expression; type B pancreatic cell development
Cellular component: RISC complex
Homologues: Orthologues: macaque mml-mir-541 (96% identical), chimpanzee MIR541 (94% identical), mouse Mir541 (74% identical), rat Mir541 (74% identical).